RET (ret proto-oncogene)
Diseases named in the same sentence as RET in open-access papers (continued):
Sharing a sentence is not in itself a finding about the gene and the disease.
tumor (continued). "We examined whether high PD-L1 expression, tumor mutational burden (TMB), and presence of targetable mutations (EGFR, BRAF, ERBB2, RET or ALK translocations, ROS1 rearrangements) occur at different frequencies in tumors from black patients compared to non-black patients." (PMID 31645901, 2019). "Targeting the RET pathway and shedding light on molecular basis of the resistance to hormone therapy may lead to new therapies in ER+ BC, improving treatment outcome and preventing tumor-related events." (PMID 35582269, 2019). "The presence of the p.G548V mutation did not correlate with clinical and pathological features (gender, tumor size, presence of metastasis, age of diagnostic) or presence or absence of other common mutations in the RET parental gene (sporadic or familial cases)." (PMID 31288802, 2019). "Thus, CCDC6, when fused to ROS1 and RET kinase, could be imagined as a predictive biomarker of resistance to conventional single mode therapy and provides indications about the tumour sensitivity to PARPi in combination with TKI in NSCLC." (PMID 29455670, 2018). "Therefore, the anti-tumor effects of regorafenib on NB may due to its combinational inhibition of RET and PDGFR-β signaling in NB cells, and the inhibition of tumor angiogenesis in the tumor microenvironment in tumor associate cells." (PMID 29262623, 2017). "Thus, the frequency of tumor-tissue EGFR M- and plasma cfDNA EGFR M+ patients is 4.0% (155/3834), which is higher than the frequencies of tumor tissue rare mutations such as ROS1, RET, BRAF, etc." (PMID 28052016, 2017). "We next examined whether alectinib induced apoptosis in tumor cells with RET fusion genes." (PMID 29088743, 2017). "Finally, and most importantly, we here reported that, upon systemic administration, the NDI derivative retained its capability to interfere with RET expression, to remarkably inhibit tumor growth and to induce apoptosis in MTC tumors grown in vivo without apparent sign of general toxicity." (PMID 27351133, 2016). "Importantly, ERK phosphorylation was moderately suppressed by NVP-AST487, highlighting a discrepancy between the in vitro and the in vivo experimental settings, potentially due to other RET-independent ERK activating signaling pathways activated by the tumor microenvironment inputs." (PMID 27602955, 2016). "To explore the chance of this situation occurring, we assessed whether the Exome Sequencing Project (ESP) exome variation database (which is not a tumour-enriched databank) included any classical disease-associated RET mutations." (PMID 25425582, 2015). "The asymptomatic RET carriers who underwent surgery benefited greatly from genetic screening and were a significantly younger age at the time of surgery and had a smaller tumor diameter compared with symptomatic patients (P < 0.001 and P = 0.007, respectively)." (PMID 25628771, 2015). "In addition, the tumour microenvironment may contribute to potentiate RET activation and signalling." (PMID 24467886, 2014). "Importantly, using in vivo models they demonstrate that tyrosine kinase inhibitors which target RET can block primary tumour growth of ER-positive breast cancers with an efficiency that is comparable with endocrine agents, the current standard of care for this subset of tumours." (PMID 24467886, 2014). "Consequently, given the current report that IL-6 promotes RET expression, the role of the GDNF–RET axis may be more relevant in those cancers characterised by an inflammatory response and an activated tumour microenvironment." (PMID 24467886, 2014). "Importantly, recombinant LIF could activate STAT3 and downregulate RET and induce tumor suppression in human MTC cells xenografted in mice, suggesting its potential as a therapeutic reagent to treat MTC." (PMID 24662939, 2014).
tumor (continued). "As cells with KIF5B/RET fusion gene overexpress the chimeric RET receptor tyrosine kinase and show spontaneous cellular transformation, inhibiting RET receptor tyrosine kinase may suppress tumor progression of KIF5B-RET fusion-positive lung cancer." (PMID 23342255, 2012). "However, alterations in other genes might contribute to this overrepresentation of RET or impact on MEN 2-related tumor development through completely different mechanisms and pathways." (PMID 23093970, 2012). "The distribution of RET/PTC rearrangement within the tumor may be also heterogeneous, from clonal RET/PTC to be present only in a small fraction of tumor cells, nonclonal RET/PTC; this fact difficults also the diagnostic and the characterization of PTC tumors." (PMID 22654559, 2011). "Down-regulation of both ERα and RET pathways may thus provide more effective anti-tumor activity." (PMID 21978374, 2011). "Several tumor models support the evidence that most of the DTCs may be due to single activating somatic mutations in one of three genes: BRAF, RAS and traslocations producing RET/PTC oncogenes." (PMID 22654562, 2011). "In this study, we carried out a comprehensive analysis of exons 5, 8 and 10–16 of RET to evaluate the prevalence of somatic mutations in a series of fifty-one sporadic MTC and to correlate with clinicopathological characteristics of the patients, including tumour ploidy pattern." (PMID 19401695, 2009). "Therefore RET/PTC3 tumours are partial and transient models of human PTC." (PMID 18985036, 2008). "Analysis of tumor tissue for the RET oncogene mutations was negative." (PMID 17997826, 2007). "Another tumor (case 2) had LOH at the RET and VHL gene locus but no somatic VHL mutation." (PMID 16707008, 2006). "Thus, a significant number of tumour cells with RET/PTC rearrangement might be misclassified, which is dependent on the interphase arrangement of chromosome 10 in the tumour nuclei and the linear distance between RET and the partner gene." (PMID 16641909, 2006). "The RET and ALK alterations were identified in a midpole nodule, whereas BRAF positivity was seen in a separate lower pole tumor." (PMID 42039113, 2026). "Tumor‐specific response analysis of NTRK and RET TKIs across various NTRK+ and RET+ solid tumors indicated a heterogeneous response with the poorest outcomes observed in CRC." (PMID 39950716, 2025). "By simultaneously inhibiting VEGFR, FGFR, PDGFRα, RET, and KIT, LEN effectively blocks tumor angiogenesis and tumor progression, leading to potent antitumor effects." (PMID 41155549, 2025). "In contrast, the persistence of RET S649L and BRAF V600E underscores their potential roles as key drivers in this patient’s tumor evolution." (PMID 40756116, 2025). "Other potential limitations include assessing for pLoF in oncogenic candidates such as RET, ROS1, FGFR4, and MYC, while FAT1 and LEF1 reported to oscillate between oncogenic and tumour suppressive behaviour." (PMID 41038821, 2025). "However, among the class III gene mutation testing results, the genes with higher abundance mutations include MKNK1, POLE, RET, RTEL1, RUNX1T1, TAP1, indicating that these gene mutations may be related to sex-cord-stromal tumors or require further research to explore unknown tumor subtypes." (PMID 40901169, 2025). "Biologically, ASCL1 plays a crucial role in tumor initiation and maintenance by regulating MYCL, SOX2, RET, BCL2, and DLL3, all of which contribute to NE differentiation and tumor survival." (PMID 40333678, 2025). "This platform enables precise 3D mapping of tumor–nerve interfaces, with implications for identifying neurotrophic signaling pathways (e.g., GDNF/Rearranged during Transfection (RET)) and screening therapeutics targeting neural recruitment in PC models." (PMID 40243726, 2025).
tumor (continued). "Anlotinib is an orally administered multi-targeted TKI that exerts antitumor effects through the simultaneous inhibition of tumor angiogenesis and tumor cell proliferation by selectively targeting FGFR, VEGFR, PDGFR, RET, and c-Kit." (PMID 41395622, 2025). "Its rearrangement, commonly seen in PTC, especially in RET/PTC1 and RET/PTC3 fusions, results in constitutive activation of RET signaling, promoting tumor growth and survival." (PMID 40507281, 2025). "Lenvatinib is a multi-targeted tyrosine kinase inhibitor that significantly inhibits tumor angiogenesis and tumor cell proliferation by targeting signaling pathways such as VEGFR1-3, FGFR1-4, PDGFRα, RET and KIT." (PMID 41451007, 2025). "We synthesise tumour-intrinsic and extrinsic neurotrophic axes, delineate neuro-immune crosstalk, and highlight interventions—TRK/RET inhibitors, CSF1R blockade, β-adrenergic antagonists—aimed at converting this liability into therapeutic leverage." (PMID 41142827, 2025). "Considering that the patient’s tumor was mainly composed of MTC, it is recommended that the patient undergo RET and BRAF gene somatic testing to evaluate the prognosis and provide a basis for targeted therapy." (PMID 41323380, 2025). "Currently, the most relevant genetic markers used by clinicians for predicting tumour behaviour are TC drivers (BRAF, RAS, or RTK, such as RET or NTRK alterations)." (PMID 40332222, 2025). "These fusions lead to ligand- and co-receptor-independent activation of the RET kinase domain (TKD), triggering downstream RAS/MAPK, PI3K/AKT, and JAK/STAT signaling that drives proliferation and tumor progression." (PMID 41465145, 2025). "Next, in an effort to profile a ROS1+ specific expression signature, transcriptomes of ROS1+ tumor samples and ROS1+ patient-derived cell lines were compared to normal lung tissue or ALK/RET+ NSCLC specimens." (PMID 39737401, 2024). "Regorafenib is an oral multi-targeted TKI, whose targets are involved in the regulation of tumor angiogenesis (VEGFR1–3 and TEK), oncogenesis (KIT, RET, RAF1, BRAF, and and BRAFV600E), and maintenance of the tumor microenvironment (PDGFRA, PDGFRB and FGFR)." (PMID 39165680, 2024). "Previous studies have demonstrated that kinases such as RET, MAP2K1, ALK, and FGF can promote tumor growth via helping tumor cells to evade the immune system by downregulating HLA-I expression." (PMID 38407266, 2024). "A rare KIF13A-RET fusion involving exon 19 of KIF13A and exon 12 of RET was detected in tumor tissue." (PMID 39057153, 2024). "The standard of care for patients with many oncogene-addicted cancers remains TKI-directed therapies, and, indeed, for rare tumors like RET and NTRK, tumor-agnostic approvals by the FDA have been forthcoming." (PMID 38339280, 2024). "GDNF can promote the proliferation and metastasis of malignant tumor cells through the RET-SRC-HER2 and RET-AKT signaling pathways." (PMID 38699694, 2024). "The findings highlight the complex interplay between genomic alterations, the tumor immune microenvironment, and clinical outcomes in ALK/RET/ROS1-rearranged NSCLC using NGS." (PMID 38397899, 2024). "However, we could not find a significant correlation between the number of SCNAs per tumor, or the presence of losses in chromosomes 22 and 9 with worse outcomes, independent of the presence of a RET variant (P = .77)." (PMID 38655100, 2024). "Regorafenib, a novel oral multi-kinase inhibitor, disrupts kinases involved in tumor angiogenesis (VEGFR1, VEGFR2, VEGFR3, TIE2), tumorigenesis (KIT, RET, RAF1, BRAF, and BRAFV600E), and the tumor microenvironment (PDGFR and FGFR)." (PMID 39687893, 2024). "In an in vivo study, vandetanib was reported to induce tumor regression in patient-derived xenograft ER-negative BC models, expressing high levels of EGFR or RET (rearranged during transfection) through the inhibition of EGFR phosphorylation." (PMID 38892472, 2024).
tumor (continued). "Further, in specimens with low DNA yield and <30% tumor content sequenced by TSO500, tier 1 fusion genes were detected in ROS1 (also reported by SOC) and RET." (PMID 38398180, 2024). "The resulting Cq values for the QfusionTM ALK, RET, or ROS1 fusion assays at a 15% tumor fraction were determined as 32.45 ± 0.17, 28.84 ± 0.25, and 25.27 ± 0.03, respectively." (PMID 38472960, 2024). "Anlotinib, by inhibiting targets such as c-Kit (proliferation), RET (proliferation), FGFR (proliferation/metastasis), and c-Met (metastasis), has been demonstrated to control tumor cell proliferation and metastasis." (PMID 39375945, 2024). "In the RAS wild-type cohort (n=9), 3/4 patients with BRAF Class II alterations and 1/4 patients with RET rearrangements qualified for RAI, with 3 SDs and 1 PR (in patient with a BRAF-altered tumor)." (PMID 37435488, 2023). "The concordance of RET fusion detection across tumor types among tissue and liquid-based NGS was 100% (8/8) in patients with greater than 1% composite tumor fraction (cTF)." (PMID 36690680, 2023). "Regorafenib is an oral multi-kinase inhibitor that targets signaling pathways involved in tumor angiogenesis (VEGFR1-3 and TIE2), oncogenesis (KIT, RET, RAF1, and BRAF), and the tumor microenvironment (PDGFR, FGFR, and CSF1R)." (PMID 37869085, 2023). "Extracellular vesicles were isolated from the blood of 28 additional NSCLC patients with tumor biopsies positive for ALK rearrangements (n = 26), RET rearrangements (n = 1), or MET∆ex14 (n = 1) by NGS, FISH, IHC, or qPCR." (PMID 37243883, 2023). "The inhibition of VEGFR2 and VEGFR3 also contributes to the remission of tumor metastasis through antiangiogenic and antiproliferative mechanisms, while the inhibition of RAF-1, RET, and KIT pathways leads to reduced cell proliferation and increased apoptosis." (PMID 38068319, 2023). "In primary PTCs, RET/PTC rearrangements correlate with young age, tumor morphology, and a high frequency of lymph node metastases." (PMID 36975488, 2023). "Both genes act as transcription factors for a regulatory subset of imprinted genes (IGs), components of the Wnt/β-Catenin pathway, and the potential drug targets RET and CYP2W1, which are also specifically overexpressed in this tumor type." (PMID 36437415, 2023). "For those low-quality and very limited samples, in situ approaches such as ALK IHC and ALK/ROS1/RET/NTRK FISH, which can also evaluate a small number of tumor cells, can be useful options." (PMID 37190044, 2023). "Patient inclusion in the registrational studies of selective RET inhibitors was limited to solid tumors with RET fusions for the NSCLC and tumor agnostic cohorts." (PMID 37627175, 2023). "Lenvatinib targets the VEGF receptors 1–3, FGF receptors 1–4, PDGF receptor α, RET, and KIT and is an effective inhibitor of tumor angiogenesis." (PMID 36902316, 2023). "Regorafenib potently blocks several protein kinases that are involved in tumor angiogenesis (VEGFRs 1–3), oncogenesis (BRAF, RAF, RET, KIT), metastasis (FGFR, PDGFR, VEGFR3) and tumor microenvironment (TME) signaling (Tie2, CSF1R)." (PMID 37620408, 2023). "Cabozantinib inhibits multiple tyrosine kinases involved in tumor growth and angiogenesis including VEGF-R2, AXL, c-MET and RET." (PMID 37435488, 2023). "The site of PPGL tumours may also vary according to the genetic cause, for example SDH mutations may be associated with tumours in the adrenal, abdomen or head and neck, while RET- and NF1-related tumours are usually located in the adrenal rather than other locations." (PMID 37761307, 2023). "In both MEN2A and MEN2B, there is a manifestation of multicentric tumor formation in the major organs such as the thyroid, parathyroid, and adrenal glands where the RET proto-oncogene is expressed." (PMID 37374115, 2023). "The study also sheds light on the molecular mechanisms involved in MTC metastasis, highlighting the crucial roles of RET, Egr-1 and STAT3 in tumor proliferation, invasion, and angiogenesis." (PMID 37046823, 2023).
tumor (continued). "Regrettably, due to the limited number of RET fusion-driven NSCLC models, as well as RET-TKI resistant ones, the molecular characterization of this adaptive tumor behavior is far from over." (PMID 36768754, 2023). "In cases with RET fusion, we identified by NGS from paraffin-embedded tumors, and we confirmed the same RET fusion in the primary tumor diagnosis in February 2014." (PMID 37371673, 2023). "This RET gene fusion was confirmed by break-apart RET FISH assay, which shows separate red and green signals in tumor cells both in Cytomatrix FFPE sections and final histological sections of surgical samples." (PMID 37686491, 2023). "The tripartite complex form (GDNF ligand+GFRα complex+RET kinase) stimulated RET by autophosphorylation and then triggered RAS, MAPK, ERK, PI3K, and AKT signaling pathways to promote tumor cell proliferation, migration, and differentiation." (PMID 36865807, 2023). "Using cell lines harboring various targetable kinase gene fusions, the limit of detection was determined to be 10% tumor cell content for ALK, ROS1, and RET rearrangements." (PMID 37628603, 2023). "In retrospective analyses, selected cancer-associated mutations and alterations that are putative targets of sitravatinib in vitro (e.g., RET, MET, CBL, AXL, KDR, and NTRK) were monitored from circulating tumor DNA in baseline plasma samples (n = 49)." (PMID 36842467, 2023). "APS03118 demonstrated marked anti-tumor efficacy in vivo in RET-driven cell-derived (Ba/F3 KIF5B-RET, V804M, TT (C634W)) and patient-derived (KIF5B-RET, CCDC6-RET, CCDC6-RET V804M) xenograft tumor models at 10 mg/kg (TGI 87–108%)." (PMID 38201460, 2023). "Administration of the multikinase inhibitor NVP-AST487 (an inhibitor of FLT3 which additionally inhibits RET, KDR, c-KIT and c-ABL at high concentrations) reduced tumor volume, corresponding to downregulation of MAPK, PI3K, and STAT1/3." (PMID 36918928, 2023). "Regorafenib is an oral multi-target kinase inhibitor, which inhibits tumorigenesis, tumor angiogenesis and tumor microenvironment by targeting VEGFR1/2/3, TIE-2, BRAF, KIT, RET, PDGFR and FGFR." (PMID 36937443, 2023). "First-generation TKIs are multi-target inhibitors that include the four main isoforms of FGFR and other signaling proteins of the tumor microenvironment, such as VEGFR, KIT, and RET." (PMID 35054474, 2022). "Transgenic RET zebrafish larvae treated with a combination of RET and FGFR inhibitors had a significant decrease in tumor volume compared with either drug alone." (PMID 35510953, 2022). "Lenvatinib is an oral multi-kinase inhibitor (MKI) that suppresses tumor cell proliferation and tumor angiogenesis via the inhibition of VEGFR1-3, FGFR1-4, PDGFR alpha, RET protein, and c-Kit protein." (PMID 36430594, 2022). "To assess the inter-tumoral heterogeneity between RET and SDHB PCPG tumor cells, we selected and re-clustered tumor cells." (PMID 36046044, 2022). "A total of 22 patients with RET-TKI, 1 with MKI, 28 with chemotherapy, and 19 with ICI-based regimens had information to assess the best tumor response." (PMID 35692799, 2022). "Pralsetinib has a significant anti-tumor effect in patients with advanced NSCLC and a RET rearrangement." (PMID 35223529, 2022). "Regorafenib can inhibit a variety of kinases involved in angiogenesis, cell proliferation, and tumor growth as well as the tumor microenvironment, mainly including VEGFR1∼3, KIT, RET, PDGFR-β, and FGFR." (PMID 37251557, 2022).